LBP (lipopolysaccharide binding protein)
Diseases named in the same sentence as LBP in open-access papers (continued):
Sharing a sentence is not in itself a finding about the gene and the disease.
infection (continued). "While low concentration of LBP enhances P-LPS responses, high LBP concentration during acute inflammation and infection inhibits P-LPS bioactivity in contrast." (PMID 32425790, 2020). "Eight plasma proteins, including APOA4, haptoglobin, MBL1, vWF, LBP, and sCD14, were affected 6 h after infection." (PMID 31803186, 2019). "Among the early response proteins in plasma, eight showed differential abundance as early as 6 h post-infection, and these included haptoglobin, Serpin A3-6, Serpin A3-8, vWF, LBP, sCD14, MBL1, and APOA4." (PMID 31803186, 2019). "During the acute inflammatory response, LBP blood levels increase and amplify the host response to infection, even at low concentrations of endotoxin." (PMID 31357597, 2019). "Some relatively new biomarkers (lipopolysaccharide-binding protein, ascites leukocyte esterase activity, lactoferrin, and bacterial DNA) were useful for diagnosing infection." (PMID 30097024, 2018). "It has been shown that tetra-acylated F. tularensis LPS cannot bind LBP, failing to activate the human polymorphonuclear leukocytes important for early infection control." (PMID 30037795, 2018). "Upon infection with Ct, the bacterial LPS is bound by LPS binding protein (LBP) and transferred to a receptor complex consisting of CD14, TLR4, and the adapter molecule MD2." (PMID 27559544, 2016). "In conclusion, absolute concentrations of LBP in blood and BALF as well as the quotient [LBP]/[BSA] in BALF perfectly paralleled the clinical course of respiratory illness after infection." (PMID 26209015, 2015). "LBP stands out from the remaining TLR4-related genes as its expression increased slowly during infection, with a maximal response at 48 h p.i.." (PMID 26018580, 2015). "LBP seems to be a promising local biomarker in the lung of calves, since its kinetics were time dependent on the course of the infection and LBP concentration as well as [LBP]/[BSA]-quotient were much higher in infected animals than in healthy controls." (PMID 26209015, 2015). "With respect to the course of infection, LBP concentrations in BALF supernatant were significantly augmented in the acute phase being about six times higher on 4 dpi compared to 14 dpi and to healthy controls." (PMID 26209015, 2015). "In support of the observed translocation of C. rodentium across the mucosal surface in the high ω-6 PUFA fed mice, we found LBP in the sera of these mice prior to infection." (PMID 23405155, 2013). "LBP is an acute-phase protein that is increased 30-fold within 24-48 h of infection and it forms complexes with bacterial lipopolysaccharides." (PMID 22348735, 2012). "LBP is constitutively present and is induced during various types of infection and inflammatory processes." (PMID 23028522, 2012). "Elevated levels of LBP, IL-6 and CRP were associated with a more severe level of infection in children." (PMID 20158885, 2010). "Elevated levels of HMGB1, LBP and PCT were associated with the presence of infection and with the presence of bacteraemia in patients with community-acquired infections." (PMID 17625012, 2007). "Lipopolysaccharide-binding protein (LBP) is an acute-phase protein that has been suggested as a marker of infection." (PMID 16569262, 2006). "The results obtained can be explained by data from other studies: higher concentrations of LBP have a protective effect against bacterial infection and may represent a physiological defense mechanism against infection." (PMID 40075763, 2025). "Notably, both sCD-14 and LBP significantly differentiate between outcome groups in the infection-free cohort, even during the early phase." (PMID 39859200, 2025). "LBP is synthesized in hepatocytes and released into the bloodstream after glycosylation, and it is commonly used as a biomarker for the lipopolysaccharide (LPS) response following gut leakage and infection." (PMID 38542520, 2024).
infection (continued). "However, we found that multiple biomarkers, including IP-10, IL-6, sCD163, leptin, IL-8, and LBP, were significantly changed in the same direction across participants, either within each participant’s two pre-infection or two post-ART-suppression specimens." (PMID 38976697, 2024). "Therefore, sCD14 and LBP production were measured in the serum of control and Plasmodium-infected 129/Sv mice, 10 days after infection." (PMID 37240201, 2023). "A concordant infection-stimulated upregulation without the influence of previous association was shown also in LBP mRNA expression." (PMID 38003758, 2023). "During acute infection phase, levels of iFABP, BG, lipopolysaccharide binding protein (LBP), soluble CD14 (sCD14), and endotoxin core antibodies (EndoCAb) are high, indicative of a loss of intestinal barrier function and an increase in the translocation of microbial products." (PMID 37004099, 2023). "The delivery of lipopolysaccharide to HDL by LBP results in the attenuation of the immune response to infection, whereas delivery of LPS by LBP to macrophage receptors initiates signal transduction pathways, resulting in the enhanced production of proinflammatory cytokines." (PMID 36361756, 2022). "Likewise, in this longitudinal study of SIV-infected, cART suppressed young macaques, a strikingly similar pattern of increase in IFABP, LBP, and sCD14 developed during the chronic phase of infection (vertical columns of the heat map)." (PMID 33717202, 2021). "Interestingly, in the case of L. interrogans, LBP was shown to be the only serum factor upregulated in the blood of patients upon infection." (PMID 32790743, 2020). "Additionally, IG count was more indicative of infection than other biomarkers including C-reactive protein, lipopolysaccharide binding protein (LBP) and IL-6." (PMID 30931316, 2019). "Furthermore, LBP was the second greatest up-regulated gene in response to the BRSV challenge infection in this study (fold change = 52)." (PMID 31611566, 2019). "Certainly, it is also possible that the localization of these two bacteria in different tissues during infection could also be a reason for the different expression levels of the LBP gene in different tissues infected with the two bacteria." (PMID 25470022, 2014). "During infection, the plasma levels of LBP, BPI and AGP can increase up to 5-fold." (PMID 23316371, 2012). "Thereby low concentrations of LBP enhance LPS-induced cell activation and may induce inflammation at local sites of infection, whereas higher concentrations of LBP can neutralize LPS-induced activation and may prevent systemic inflammation." (PMID 21901123, 2011). "Lipopolysaccharide binding protein (LBP), a key participant in the inflammatory response to infection, may be a useful marker for diagnosis and prognosis of patients with bacterial infections." (PMID 19718443, 2009). "Our study data suggest that LBP (cut off level 20 μg/ml), CRP (cut off level 30 mg/l) and IL-6 (cut off level 16.3 pg/ml) are comparable in terms of their diagnostic abilities in diagnosing infection." (PMID 16569262, 2006). "In addition to LPS activity itself, the serum concentration of its binding proteins such as LPS-binding protein (LBP) and the endogenous anti-endotoxin core antibodies (EndoCAb) IgM and IgG can serve as markers of infection severity and the host’s anti-inflammatory response." (PMID 38137490, 2023). "However, the pro-infection effect of heparin was also reported in an in vitro study, showing that heparin facilitates LPS entry and activation of peripheral blood monocytes by binding to LPS-binding protein (LBP) and inducing IL-8 release." (PMID 36865384, 2023). "Moreover, lipopolysaccharide binding protein could control infection by binding to LPS and transferring it to the receptor on the surface of macrophages." (PMID 35479637, 2022). "Infection with D. fragilis was associated with higher LBP levels but adding this variable into the model did not alter the effect of SES on LBP." (PMID 35233023, 2022).
infection (continued). "Additionally, LBP transfers LPS to very-low-density lipoproteins, low-density lipoproteins, high-density lipoproteins or chylomicrons, contributing to immune reaction against the infection." (PMID 34295331, 2021). "Furthermore, we speculated that significantly increased LBP in CAD revealed the underlying imbalance of the immune system and increased the risk of infection in CAD subjects." (PMID 32508734, 2020). "Moreover, LBP upregulation during the infection has seemingly a dual function." (PMID 26798659, 2015). "In addition, in our study population, we found significantly higher LBP concentrations in patients with atypical infections compared with patients infected with an unknown pathogen." (PMID 22348735, 2012). "Interestingly, the increased expression of ESE-1, STAT5A, AHRNT, LBP coupled with decreased expression of C/EBPα indirectly suggests that microbial translocation is occurring early in infection even though data from peripheral blood show modest evidence of elevated LPS in circulation." (PMID 22511950, 2012). "Therefore, the degree of correlation between CRP and LBP may vary, dependent on the individual contribution of extrahepatic sources according to the site of infection." (PMID 21901123, 2011). "Of the 9 TN-specific proteins, 6 proteins (CRP, LBP, LRG1, SAA1, TFRC) overlapped with the WT group identifying them as infection-specific and toxin-independent proteins (black text)." (PMID 41326716, 2026). "The infection with S. Typhimurium significantly increased TLR4, MD‐2, LBP, CD14, and MyD88 mRNA in both parts of the intestine." (PMID 41474380, 2026). "Haptoglobin, SAA, and LBP are APP and can bind bacterial endotoxins and are used to evaluate systemic responses to infection, inflammation, or trauma." (PMID 40202033, 2025). "The expression level of several proinflammatory genes including TYROBP, S100A8, S100A11, LBP and CD88 were increased significantly after infection." (PMID 39398025, 2024). "After binding, LBP then presents LPS to cell surface pattern recognition receptors (PRRs) such as CD14 and TLR4, to elicit subsequent immune response to infection." (PMID 38542520, 2024). "LBP/BPI 3.1 and 3.2 were over-expressed at day 25 after primary infection and following the secondary challenges compared to naïve snails, while all other genes of this family were under-expressed in all infection conditions." (PMID 34070104, 2021). "We found that infection with the wild-type S. Typhimurium upregulated mRNA in the terminal ileum in all analyzed members of the TLR4 signaling pathway—TLR4, MD-2, CD14, and LBP." (PMID 32842482, 2020). "Lipopolysaccharide-binding protein (LBP), an acute-phase protein produced by hepatocytes, is found to be a biomarker able to predict the development of severe infection in LC patients." (PMID 32280697, 2020). "At 2 months post-infection (M2), plasma sCD14 showed the most significant fold difference compared to HIV-uninfected individuals (P < 0.0001), followed by plasma LBP and ASCA IgG (P = 0.0025 and P = 0.0159)." (PMID 31185037, 2019). "Meanwhile, MyD88, LBP and TLR4 probably play an important role in stimulating immune and antigen presentation in piglet’s response to the infection of E. coli F18." (PMID 27809935, 2016). "Acute phase proteins (APPs), such as serum amyloid A (SAA), haptoglobin (Hp) and LPS-binding protein (LBP), are biomarkers for the diagnosis of inflammation and infection." (PMID 25889631, 2015). "Laboratory parameters in use for the rapid identification of infection include procalcitonin (PCT), interleukin 6 (IL-6), lipopolysaccharide binding protein (LBP), and CRP." (PMID 24349403, 2013). "The five clinical parameters, IG#, CRP, LBP, IL-6 and SOFA score were analyzed for their discriminative power to diagnose infection." (PMID 23398965, 2013). "Our study showed that the detectable levels LBP, IL-6 and CRP differ in the earl stage of infection dependent on severity of infection." (PMID 20158885, 2010).
infection (continued). "However, recent studies have revealed that some inflammatory markers such as the high-mobility group box-1 protein (HMGB1), the lipopolysaccharide-binding protein (LBP) and the Interleukin-6 (IL-6) may be detectable already in the early state of infection and bacteraemia." (PMID 20158885, 2010). "The mean baseline LBP serum level was 122.5±74 μg/mL (range 26.9–334.0 μg/mL) without significant differences between age, gender, APACHE II score or source of infection." (PMID 19718443, 2009). "Levels of all studied inflammatory markers (HMGB1, LBP, PCT, IL-6) and infection markers (C-reactive protein, white blood cell count, neutrophils) were elevated among bacteraemic patients." (PMID 17625012, 2007). "In aSAH patients without infection, differences in LBP and sCD-14 levels between outcome groups suggest potential endotoxin release from microbial systems, contributing to neuroinflammation and influencing outcomes." (PMID 39859200, 2025). "In our study, the serum levels of LBP and sCD-14 were significantly higher in the unfavorable outcome group among aSAH patients without in-hospital infection." (PMID 39859200, 2025). "The expression of C6, C7, IRAK4, LBP, and RIPK2 was significantly upregulated after infection with A. hydrophila, while the expression of SIPA1L2 and NFATC1 was significantly downregulated after infection." (PMID 36910190, 2023). "Higher WBC counts and higher percentage of neutrophil without infection are likely a result of a LPS-induced proinflammatory state with elevated LBP and CRP as well." (PMID 33753837, 2021). "During the observation period, LBP levels increased in five animals (1.2- to 2.6-fold) after infection demonstrating the enhanced translocation of gram-negative bacterial components into systemic circulation." (PMID 32616803, 2020). "LPS-activated NF-κB in combination with LBP, and triggers the pro-inflammatory mediators of APR, such as IL-1β, IL-6 and TNF-α produced by macrophages or blood monocytes at the site of injury or infection." (PMID 28596485, 2017). "The correlation analysis revealed a significant correlation between LBP and CRP at 6 h (P <0.001), 12 h (P = 0.003) and 3 d (P <0.001), IL-10 and IL-6 at 7 d (P <0.001), and IL-6 and CRP at 7 d (P = 0.001) in patients with infection." (PMID 25613713, 2015). "Likewise, LPS-binding protein (LBP) and myeloid differentiation primary response 88 (MYD88), also involved in TLR4 signaling, were significantly up-regulated after infection." (PMID 26018580, 2015). "In contrast, there was no induction of LBP in mice fed ω-3 PUFA supplements prior to infection but during infection LBP levels increased." (PMID 23405155, 2013). "Among the biomarkers evaluated in the present study, the best parameter was LBP with a median level of 26.2 pg/ml in patients with infections and a median level of 19.1 pg/ml in those without infections." (PMID 24349403, 2013). "LBP is a major LPS-binding protein in the mammalian biological system, which facilitates the transfer of LPS to the membrane-bound CD14 receptor and then induces inflammation at local sites of infection." (PMID 23799041, 2013). "Infection with SARS-CoV-2 did not change plasma LBP levels in either men or women." (PMID 39997462, 2025). "Interestingly, a similar enhancement of sCD14 and LBP production was found after mouse infection with LDV, a virus that does not affect the gut but that also enhances the susceptibility of its host to endotoxin shock." (PMID 37240201, 2023). "Although statistically non-significant, relatively lower plasma lipopolysaccharide binding protein levels were detected in THC/SIV (n = 5) (average 46 ng/ml) compared to VEH/SIV rhesus macaques (n = 4) (average 25 ng/ml) at 180 days post infection." (PMID 31114576, 2019).
infection (continued). "Acute phase proteins, such as C-reactive protein (CRP), Serum Amyloid A2 (SAA2), and Lipopolysaccharide binding protein (LPS-BP) were increased several fold in both infection types, but were not present at high enough levels to be quantitated in the naive NHP plasma samples." (PMID 30774579, 2019). "Interestingly, BPI/LBP was up-regulated only after infection with live A. salmonicida but not in presence of formalin-killed A. salmonicida." (PMID 31231379, 2019). "In addition, we showed that LBP - as an acute-phase protein – not only increases in patients with infection but also increases in patients without infection during the first day in response to the infarction." (PMID 25613713, 2015). "Furthermore, the levels of LPS and LBP were not correlated with presence of infectious virus and route of infection." (PMID 25759828, 2014). "Infection of the uterus is accompanied by systemic fluctuations of inflammatory cytokines like tumor necrosis factor (TNF), interleukin (IL)-1, IL-6, and acute phase proteins (APP) such as lipopolysaccharide-binding protein (LBP), serum amyloid A (SAA), and haptoglobin (Hp)." (PMID 25919010, 2014). "Although there is almost no literature regarding LBP in M. tuberculosis infection, its abnormal change in the serum of patients with ATB suggests that it may be associated with the infection of M. tuberculosis, but its roles in the infection process has not yet been discovered." (PMID 35069505, 2021). "Notably, our previously reported biomarker, LBP, also failed to differentiate aGvHD from infection." (PMID 23505556, 2013). "Other features of pleural fluid analysis that discriminate infection from inflammation in the complicated versus noncomplicated setting include pleural soluble triggering receptor of myeloid cells-1 (sTREM-1), procalcitonin, and lipopolysaccharide binding protein (LBP)." (PMID 22448326, 2012). "In the group without infection (n = 116), we performed a correlation analysis between serum CRP levels and early (D1) and late (D9) LBP and sCD-14 values." (PMID 39859200, 2025). "In the univariate analysis, levels of LBP, IL-10, IL-6 and CRP were compared between patients with and without infection." (PMID 25613713, 2015). "Surprisingly, we also observed a moderate, but noticeable rise in LBP and CRP plasma levels from day 7 to day 14 in patients of the surviving group without any evidence for a new or recurrent infection." (PMID 21901123, 2011). "In patients who developed an infection (n = 61) during hospitalization (median [IQR] serum level of CRP during hospitalization: 73.4), we did not observe any difference in serum levels of LBP or sCD-14 between the favorable and unfavorable outcome groups at any measurement time point." (PMID 39859200, 2025).